SRGN (serglycin)
Diseases named in the same sentence as SRGN in open-access papers (continued):
Sharing a sentence is not in itself a finding about the gene and the disease.
cancer (57 papers, 2012 to 2026). A tumor composed of atypical neoplastic, often pleomorphic cells that invade other tissues. "Serglycin, an intracellular PG and secreted by cancer cells, linked to either Hep or CS chains, can bind to cell surface receptors and modulate cell function." (PMID 39334952, 2024). "There is mounting evidence that a wide range of glycans, including proteoglycans like syndecans, agrin, serglycin, SLRPs and others, hyaluronan, sialylated proteins, and O-linked glycans, are involved in cancer cell mechanotransduction." (PMID 36693448, 2023). "Among the non-NFκB/TNF hallmark genes that received votes across all 16 cancer types, four genes (SRGN, CCN2, TNFRSF12A, and ZFP36L1) with an average vote exceeding 900 have been reported as regulated by TNF and NFκB." (PMID 37475016, 2023). "Elevated serglycin expression was reported for cancer cells in patient tissues and has been linked to aggressive cancer cell phenotypes in vitro." (PMID 32984308, 2020). "Serglycin secreted by both cancer-associated stroma cells, as well as the cancer cells themselves, binds to the transmembrane glycoprotein CD44." (PMID 33330449, 2020). "It demonstrates that SRGN is crucial for regulating actin cytoskeletal organization associated with cell migration for cancer metastasis." (PMID 31242922, 2019). "Serglycin proteoglycans are also expressed in cancer cells where increased expression has been linked to poor prognosis." (PMID 27223472, 2016). "The detailed mechanism underlying the roles of serglycin in cancer progression remains to be clarified." (PMID 27809309, 2016). "It is worth noticing that aggressive cancer cells that harbor KRAS or EGFR mutations secreted serglycin constitutively in elevated levels." (PMID 26581653, 2015). "We have analyzed late stage tumors in wild type and serglycin deficient mice in the RIP1-Tag2 model at a stage where invasive carcinomas have developed." (PMID 25978773, 2015). "We have analyzed late stage tumors in wild type and serglycin deficient mice in the RIP1-Tag2 model at a time point where invasive carcinomas have developed." (PMID 25978773, 2015). "Cancer associated fibroblasts which are activated by cancer cells also overexpress inflammatory mediators as well as serglycin and a disintegrin and metalloproteinase with thrombospondin motifs 1 (ADAMTS1), promoting cancer cell invasion." (PMID 24455486, 2014). "SRGN encodes a hematopoietic granule proteoglycan protein associated with apoptotic processes in the development of cellular tissues and is up-regulated in various cancers." (PMID 39816677, 2025). "Mechanistically, serglycin can activate several cancer-associated signaling pathways in other types of cancer, including mitogen-activated protein kinase (MAPK)/β-catenin signaling, transforming growth factor-β2 (TGF-β2) signaling via interaction with CD44, and the NF-κB pathway." (PMID 30297672, 2018). "Serglycin is secreted in elevated levels in cancer cells mutated in KRAS or HER1/EGFR, the fact that may suggest an implication of EGFR-RAS pathway in the biosynthesis and more importantly in secretion of serglycin." (PMID 26581653, 2015). "Interestingly, SRGN, a secretory factor produced by CAFs, has been reported to be highly expressed in various cancers—including breast, lung, nasopharyngeal, and oesophageal—and is associated with promoting cancer invasion, metastasis, and chemoresistance." (PMID 41410182, 2025). "Serglycin (SRGN) is involved in the progression of various cancers, and its overexpression is related to poor prognosis in HCC patients." (PMID 40384866, 2025). "Collectively, these findings demonstrate that SRGN plays a pivotal role in regulating cancer stem cell-like characteristics in HCC cells." (PMID 40384866, 2025). "The levels of serglycin in this case are likely attributed to immune and myeloid cells, requiring further studies to determine the exact molecular mechanisms in each cancer type." (PMID 40542654, 2025).
cancer (continued). "Despite the vital roles of SRGN in regulating cancer progression and immune response, few studies were aimed to investigate the role of SRGN in the central nervous system." (PMID 38287411, 2024). "Although serglycin is considered as an intracellular proteoglycan, recent studies have shown that serglycin can be secreted by cancer cells and bind to cell surface receptors." (PMID 36693448, 2023). "In recent years, it has been demonstrated that serglycin is also expressed by several other cell types, such as endothelial cells, muscle cells, and multiple types of cancer cells." (PMID 35494005, 2022). "In both subtypes, we detected expression of serglycin in both the cancer cells and in infiltrating immune cells." (PMID 35494005, 2022). "SRGN has been demonstrated to be overexpressed in many cancers and is closely related to the occurrence and development of tumors." (PMID 36133820, 2022). "Taken together, these data showed that SRGN upregulates MDK expression in ESCC cells and promotes its secretion in a GAG-dependent manner, and that SRGN-induced MDK contributes to cancer cell invasion." (PMID 33456569, 2021). "Although the involvement of SRGN in tumorigenesis has been investigated in many human cancers, the detailed mechanisms are still far from being fully understood." (PMID 32292495, 2020). "SRGN overexpression was found in a variety of cancers and is correlated with the development, progression, and aggressive biological behavior of tumors 14-18." (PMID 32292495, 2020). "Other than hematopoietic malignancies, several solid tumors were reported to overexpress SRGN, and increased expression of SRGN correlated with aggressive phenotypes in cancers of lung, breast, and nasopharynx." (PMID 31898491, 2020). "Serglycin is highly expressed in aggressive cancer cells and its post-translational modification (glycanation) and its efficient secretion are required to induce growth, migration, and invasion." (PMID 33543032, 2020). "Further, serglycin was identified as an unfavorable prognostic factor in patients suffering from a range of cancers, including glioblastoma, liver, lung, and nasopharynx." (PMID 32984308, 2020). "Considering this intriguing observation, further studies are warranted to better understand the regulation of mechanosignaling by serglycin in cancer cells." (PMID 33330449, 2020). "SRGN expressed by carcinoma and the stromal cells was readily secreted to the TME, and SRGN binds to tumor cell surface receptor CD44 and activates downstream signaling pathways, promoting malignant phenotypes." (PMID 31898491, 2020). "Recent studies have demonstrated that serglycin is overexpressed in a variety of cancers, including colon, breast, and lung cancers, and that serglycin overexpression was correlated with a more aggressive malignant phenotype." (PMID 30297672, 2018). "Our previous studies have also found that the low-metastatic cancer cells can be promoted to possess more aggressive behaviors by high-metastasis cancer cells via serglycin and interleukin-8 (IL-8) signaling." (PMID 26747273, 2016). "We found that serglycin was expressed and constitutively secreted in culture medium in high levels in more aggressive cancer cells." (PMID 26581653, 2015). "Our study further strengthens serglycin as a relevant molecule for more extensive mechanistic studies in the context of cancer pathology." (PMID 25978773, 2015). "Most previous studies have focused on serglycin in hematopoietic cells, although serglycin is also expressed by other cells including smooth muscle cells, cancer cells, endothelial cells and adipose tissue." (PMID 26694746, 2015). "Since little is known on the expression of serglycin in solid tumors, we went on to study the expression and distribution of serglycin in cancer cell lines and malignant tissues." (PMID 26581653, 2015). "Our study investigated for first time the distribution of serglycin in normal epithelial and cancerous lesions in most common cancer types." (PMID 26581653, 2015).
cancer (continued). "Although a limited number of cases were examined, our data have shown a strong diffuse cytoplasmic distribution for serglycin in more aggressive cancer cells in most cases." (PMID 26581653, 2015). "It is worth noticing that aggressive NCI-H23 and DLD-1 cancer cells expressing low mRNA levels for serglycin secreted significant amounts of this proteoglycan." (PMID 26581653, 2015). "The results of the present pilot study reveal that serglycin is highly expressed and secreted by more aggressive cancer cells." (PMID 26581653, 2015). "Few recent studies have demonstrated the overexpression of serglycin by aggressive cancer cells in tumors." (PMID 26581653, 2015). "The upregulated biosynthesis and secretion of glycanated serglycin by cancer cells promote their growth, migration, and invasion and are correlated with poor prognosis." (PMID 26581653, 2015). "It has been shown that serglycin expression is markedly upregulated in cancer-activated fibroblasts among other inflammatory mediators and a disintegrin and metalloproteinase with thrombospondin motifs 1 (ADAMTS-1) promoting cancer cell invasion." (PMID 26581653, 2015). "The pattern of cytoplasmic staining was granular suggesting the packaging of serglycin in secretory granules within cancer cells." (PMID 26581653, 2015). "It is of interest that serglycin is shown to affect the migratory capacity of cancer cells, suggesting an effect of serglycin on migration also in endothelial cells." (PMID 26694746, 2015). "The promotion of an aggressive cancer cell phenotype by serglycin overexpression was confirmed by stable transfection of low aggressive MCF-7 cells with serglycin cDNA." (PMID 24205138, 2013). "Elevated expression of serglycin promotes aggressiveness of nasopharygeal cancer cells and correlates with the formation of distant metastases." (PMID 24205138, 2013). "Silencing of serglycin in nasopharygeal cancer cells significantly inhibited cancer cell migration and invasion suggesting a critical role for serglycin in cancer cell spread." (PMID 24205138, 2013). "This stimulatory effect of serglycin in the promotion of cancer cell growth, migration and invasion was abolished by removing the GAG attachment sites and thus deletion of GAG chains from the serglycin molecule." (PMID 24205138, 2013). "Cancer cells and fibroblasts exhibit low SRGN expression in the analyzed sample cohort." (PMID 35494005, 2022). "However, serglycin has now been demonstrated to be expressed by diverse cell types such as muscle cells, chondrocytes, endothelial cells, and several types of cancer cells." (PMID 35494005, 2022). "CXCL8 and LAPTM5 proteins have been reported to promote cell activity, TMEM156 and LGALS1 proteins enhance cell invasion, VIM and LGALS1 proteins induce cell migration, FABP5 and SRGN proteins activate cancer metastasis, and the DEFB4A protein regulates immunity in human cancers." (PMID 35632763, 2022). "In recent years, studies have shown that SRGN also play important roles in cancer." (PMID 34556636, 2021). "However, the mechanisms of SRGN and its molecular interactions during cancer progression are far from being fully understood." (PMID 33456569, 2021). "In view of the increased expression and important role of SRGN in chemoresistant BC cells and the involvement of regulatory feedback loops in cancer, we sought to determine whether SRGN- regulated YAP could regulate SRGN expression via a feedback mechanism." (PMID 32292495, 2020). "Overexpression of SRGN has been reported in several types of cancers." (PMID 32292495, 2020). "Serglycin is overexpressed in aggressive cancers suggesting its protumorigenic role." (PMID 28445977, 2017). "Serglycin has been reported to be overexpressed in human cancers." (PMID 28445977, 2017).
cancer (continued). "Serglycin proteoglycan is the dominant proteoglycan species in most hematopoietic cells including MCs and it is also expressed in non-hematopoietic cells like endothelial cells, fibroblasts and certain aggressive cancer cells." (PMID 28445977, 2017). "However, the exact role of serglycin in these pathways during cancer progression remains to be elucidated." (PMID 27223472, 2016). "In some cancer cells serglycin also exhibited membrane and/or nuclear immunolocalization." (PMID 26581653, 2015). "The overexpression of serglycin by cancer and stromal cells may augment the expression of inflammatory mediators, growth factors, and proteolytic enzymes." (PMID 26581653, 2015). "A similar function of serglycin in cancer cells cannot be excluded." (PMID 26581653, 2015). "Our findings that serglycin is markedly synthesized by cancer and stromal cells in malignant tissues may propose a role for serglycin in cancer progression." (PMID 26581653, 2015). "In order to evaluate whether serglycin is secreted in the culture medium of cancer cells, they were cultured in serum-free medium and supernatants were collected and concentrated." (PMID 26581653, 2015). "The elevated levels of serglycin in aggressive cancer and stromal cells may suggest a key role for serglycin in disease progression." (PMID 26581653, 2015). "Interestingly, the intensity of serglycin immunoexpression was augmented at the invasive front of the carcinomas." (PMID 26581653, 2015). "Considering that single GAG chains and serglycin interact with growth factors, cytokines, and chemokines, it is plausible that serglycin secreted by cancer and stromal cells is important for the protection of inflammatory mediators in ECM and the creation of chemotactic gradients." (PMID 24455486, 2014). "Indeed we found SRGN expression to be high in these cancers with a correlation to malignancy grade." (PMID 28445977, 2017). "However, the serglycin-dependent mediators promoting cancer progression remain to be determined." (PMID 27223472, 2016). "Also, the involvement of serglycin in inflammation, proliferation and angiogenesis may implicate serglycin in several cancers." (PMID 26694746, 2015). "This led to pSTAT3-mediated activation of cancer stemness genes (IGFN1, EML1, and SRGN), contributing to Adriamycin resistance." (PMID 40696387, 2025). "Extensive studies have revealed that CD44 mediates cancer initiation and progression through interactions with its ligands, including but not limited to HA, OPN, serglycin, CS, the MMPs family, and FN." (PMID 38783892, 2024). "In the present study, overexpression of SRGN in ESCC cells altered the protein profile of exosomes, and endowed the SRGN Exo with the capability to promote cancer progression through autocrine and paracrine mechanisms." (PMID 36632458, 2023). "Serglycin (SRGN), a proteoglycan secreted from cancer cells and CAFs, renders chemoresistance and EMT features via a CD44-dependent NF-κB activation." (PMID 34760886, 2021). "These include POLK, NIFK, SRGN, CAMP, CD109, and PLAC1 that are upregulated in several cancers resulting in metastasis and poor prognosis." (PMID 33110154, 2020). "Serglycin induces multiple pro-tumorigenic signaling pathways evoking EMT and cancer stem cell properties in several cancer cell types." (PMID 33543032, 2020). "Multiple investigations show the oncogenic roles of SRGN, FLI1, and MACROH2A2 in various cancers." (PMID 39816677, 2025). "The roles of SRGN, FLI1, and MACROH2A2 in carcinogenesis within other cancers are established, yet their mechanisms of action in uEVs of BC remain unclear." (PMID 39816677, 2025). "Then, a pan-cancer differential expression analysis was performed, and we found that genes such as CXCL13, ITM2A, NR3C1, SRGN, COTL1, and PDCD1 were significantly up-regulated in SC-2 cells compared with other cells in at least five cancer types, but not in SC-10 cells." (PMID 36049666, 2023).
cancer (continued). "Indeed, we highlighted three pan-cancer NFκB/TNF hallmark genes (EGR1, JUNB, and ZNF36) and identified four candidates (SRGN, CCN2, TNFRSF12A, and ZFP36L1) that are highly potentially involved in NFκB/TNF pathways in various cancers." (PMID 37475016, 2023). "Reports documenting that SRGN promotes cancer cell aggressiveness and metastasis through several signaling pathways, including CD44/NF-κB/CLDN1 axis, HIF-1α/SRGN axis, and SRGN/TGFβ2 axis, may further support our observations presented here." (PMID 34059749, 2021). "All cancer cells analyzed till now synthesize serglycin, which is modified with CS chains and not heparin as in mast cells." (PMID 26581653, 2015). "Treatment of cancer cells with exogenously added glycanated serglycin promoted cancer cell metastasis and invasion, whereas non-glycosylated core protein of serglycin failed to induce cell motility." (PMID 24455486, 2014). "As shown in previous studies, the overexpression of serglycin is correlated with the establishment of more aggressive mesenchymal cancer cell phenotype and promotes cancer cells proliferation, especially in nonadhesive matrices, migration, and invasion both in vitro and in vivo." (PMID 26581653, 2015). "Furthermore, serglycin expression levels were an independent predictor of overall survival and time to recurrence in HCC patients, suggesting that it could predict a malignant phenotype similar to other types of cancer." (PMID 30297672, 2018). "Similarly, serglycin overexpression did not affect the proliferation of nasopharygeal cancer cells." (PMID 24205138, 2013). "The same phenomenon was found in the TCGA pan-cancer cohort, in which ESCA and many other cancer types were found to have higher SRGN expression compared with non-neoplastic tissue." (PMID 33456569, 2021).